GSPT2 (G1 to S phase transition 2)
Description:
GTPase component of the eRF1-eRF3-GTP ternary complex, a ternary complex that mediates translation termination in response to the termination codons UAA, UAG and UGA. GSPT2/ERF3B mediates ETF1/ERF1 delivery to stop codons: The eRF1-eRF3-GTP complex binds to a stop codon in the ribosomal A-site. GTP hydrolysis by GSPT2/ERF3B induces a conformational change that leads to its dissociation, permitting ETF1/ERF1 to accommodate fully in the A-site. Component of the transient SURF complex which recruits UPF1 to stalled ribosomes in the context of nonsense-mediated decay (NMD) of mRNAs containing premature stop codons.
Synonyms: eRF3b; FLJ10441; GST2
Tractability: PROTAC: ubiquitination databases record sites on it; its protein half-life has been measured; a small molecule that binds it is known.
Gene: Protein-coding gene on chromosome X (51,743,442 to 51,746,232, forward strand). Ensembl gene ENSG00000189369.
Subcellular location: Cytoplasm
Subcellular location (Human Protein Atlas): Cytosol
Pathways (Reactome):
Metabolism of RNA: Nonsense Mediated Decay (NMD) enhanced by the Exon Junction Complex (EJC); Nonsense Mediated Decay (NMD) independent of the Exon Junction Complex (EJC)
Developmental Biology: Regulation of expression of SLITs and ROBOs
Metabolism of proteins: Eukaryotic Translation Termination
Gene Ontology:
Molecular function: GTPase activity; protein binding; RNA binding; translation release factor activity; GTP binding
Biological process: translational termination; translation
Cellular component: cytosol; translation release factor complex; cytoplasm
Homologues: Orthologues: macaque GSPT2 (94% identical), pig GSPT2 (93% identical), rabbit GSPT2 (93% identical), guinea pig GSPT2 (93% identical), rat Gspt2 (90% identical), mouse Gspt2 (90% identical), tropical clawed frog 42sp50 (24% identical), zebrafish eef1a1l3 (23% identical), Drosophila melanogaster mEFTu2 (16% identical), Caenorhabditis elegans tufm-2 (15% identical), Caenorhabditis elegans eif-2gamma (13% identical), Drosophila melanogaster eIF2gamma (13% identical), and 2 more. Paralogues in human: GSPT1 (88% identical), EEF1A1 (25% identical), EIF5B (25% identical), EEF1A2 (25% identical), HBS1L (22% identical), TUFM (17% identical), GTPBP1 (17% identical), GTPBP2 (16% identical), MTIF2 (14% identical), EIF2S3 (14% identical), EIF2S3B (14% identical), EEF2 (13% identical), and 6 more.
Diseases named in the same sentence as GSPT2 in open-access papers:
GSPT2 is named in the same sentence as 15 diseases in open-access papers, as found by Europe PMC text mining. Sharing a sentence is not in itself a finding about the gene and the disease. The quoted sentences say what the papers report.
hepatocellular carcinoma (2 papers, 2014 to 2022). A malignant tumor that arises from hepatocytes. "GSPT2 is a GTPase that mediates translation termination and has been reported to be a biomarker for hepatocellular carcinoma and CRC liver metastasis in serum." (PMID 35589723, 2022).
liver disease (2 papers, 2019 to 2021). "So we considered eRF3b/GSPT2 is probably associated with the development of HBV-related liver disease." (PMID 30867251, 2019). "The functions and mechanisms of eRF3b/GSPT2 and 4210 Da in liver disease are not clear at present and are worth further study." (PMID 34417517, 2021).
breast carcinoma (1 paper, 2023). "In this study, our risk model based on TIPARP, SAMD4A, TSEN54, GSPT2, and RNASE1 was compared with the high and low risk groups of breast cancer cell lines in the CellMiner database." (PMID 36911389, 2023). "Consistent with the trend of results from public databases, TSEN54 was upregulated in breast cancer cell lines and GSPT2, RNASE1, SAMD4A, and TIPARP were downregulated in breast cancer cell lines." (PMID 36911389, 2023). "GSPT2, SAMD4A, and TIPARP are downregulated in ECM-receptor interaction pathways, which play important roles in tumor shedding, adhesion, degradation, motility, and proliferation and may be involved in breast cancer development." (PMID 36911389, 2023).
chronic hepatitis B (1 paper, 2021). "The relative expression of GSPT2/18S rRNA in patients with chronic hepatitis B is higher than that in patients with LC or HCC16, consistent with the expression of 4210 Da in the serum in this study." (PMID 34417517, 2021).
colorectal cancer (1 paper, 2023). A primary or metastatic malignant neoplasm that affects the colon or rectum. "Similarly, GSPT2 was discovered to be the most distinct and singular factor in stage II colorectal cancer patients when evaluating the difference in gene expression between stage II and stage III patients." (PMID 36911389, 2023).
developmental delay (1 paper, 2017). "Loss of GSPT2 and/or MAGED1 function may contribute to the intellectual disability and developmental delay seen in males with these deletions." (PMID 28414775, 2017).
Intellectual disability (1 paper, 2017). "Duplications of GSPT2 have been documented in individuals with intellectual disability, but the phenotypic consequences of a loss of GSPT2 function have not been elucidated in humans or mouse models." (PMID 28414775, 2017).
liver cancer (1 paper, 2023). An epithelial or non-epithelial malignant neoplasm that arises from the liver. "In comparison to liver cancer patients, the normal control group’s blood had greater levels of GSPT2 expression in other malignancies." (PMID 36911389, 2023).
Sepsis (1 paper, 2025). Sepsis is defined as life-threatening organ dysfunction caused by a dysregulated host response to infection. "Notably, six of these genes, including GSPT2, SMCHD1, SF3B1, DDX3X, and F3, showed significant differences and consistent trends between sepsis and septic ARDS samples in the GSE66890 and GSE32707 databases." (PMID 39854144, 2025).
cancer (3 papers, 2014 to 2025). A tumor composed of atypical neoplastic, often pleomorphic cells that invade other tissues. "As GSPT2 is a substitute for GSPT1, the dysregulation of GSPT2 may result in cancer drug resistance to GSPT1‐targeted therapy." (PMID 41194439, 2025).
GSPT2 also shares sentences with these, for which no sentence is quoted: tumor (3 papers); hepatitis B virus infection (1); multiple myeloma (1); Obesity (1); X-linked intellectual disability (1).